VPS33B (VPS33B late endosome and lysosome associated)
Description:
May play a role in vesicle-mediated protein trafficking to lysosomal compartments and in membrane docking/fusion reactions of late endosomes/lysosomes. Required for proper trafficking and targeting of the collagen-modifying enzyme lysyl hydroxylase 3 (LH3) to intracellular collagen. Mediates phagolysosomal fusion in macrophages. Proposed to be involved in endosomal maturation implicating VIPAS39. In epithelial cells, the VPS33B:VIPAS39 complex may play a role in the apical recycling pathway and in the maintenance of the apical-basolateral polarity. Seems to be involved in the sorting of specific cargos from the trans-Golgi network to alpha-granule-destined multivesicular bodies (MVBs) promoting MVBs maturation in megakaryocytes (By similarity).
Synonyms: FLJ14848; KDIDAR; PFIC12
Tractability: Antibody: UniProt places it where antibodies can reach, with medium confidence. PROTAC: ubiquitination databases record sites on it; its protein half-life has been measured.
Gene: Protein-coding gene on chromosome 15 (90,998,673 to 91,022,603, reverse strand). Ensembl gene ENSG00000184056.
Subcellular location: Late endosome membrane; Lysosome membrane; Early endosome; Cytoplasmic vesicle, clathrin-coated vesicle; Recycling endosome
Pathways (Reactome):
Disease: Prevention of phagosomal-lysosomal fusion; SARS-CoV-2 modulates autophagy
Gene Ontology:
Molecular function: protein binding; protein-containing complex binding; AP-3 adaptor complex binding
Biological process: autophagosome maturation; collagen metabolic process; endosome organization; endosome to lysosome transport; lysosome localization; melanosome localization; membrane fusion; peptidyl-lysine hydroxylation; platelet alpha granule organization; protein transport; skin morphogenesis; vesicle-mediated transport; phagosome-lysosome fusion; megakaryocyte development; regulation of platelet aggregation
Cellular component: clathrin-coated vesicle; cytoplasm; early endosome; early endosome membrane; endosome; Golgi apparatus; HOPS complex; late endosome; late endosome membrane; lysosomal membrane; lysosome; perinuclear region of cytoplasm; platelet alpha granule; recycling endosome; vesicle tethering complex; cytosol; endosome membrane
Genetic constraint (gnomAD): Loss-of-function variants: 80 observed, 99.26 expected, observed/expected ratio (o/e) 0.81, 90% interval 0.67 to 0.97. The upper end of that interval is the gene's LOEUF score, 0.97, which puts it in group 4 of 6, group 1 being the genes least tolerant of losing a copy. Missense variants: 715 observed, 800.13 expected, observed/expected ratio (o/e) 0.89, 90% interval 0.84 to 0.95. Synonymous variants: 280 observed, 290.39 expected, observed/expected ratio (o/e) 0.96, 90% interval 0.87 to 1.07.
Gene-disease validity (ClinGen):
ClinGen rates the evidence that VPS33B causes each of these diseases.
arthrogryposis, renal dysfunction, and cholestasis 1 (autosomal recessive): Definitive.
Homologues: Orthologues: chimpanzee VPS33B (99% identical), rabbit VPS33B (98% identical), dog VPS33B (97% identical), pig VPS33B (97% identical), mouse Vps33b (97% identical), guinea pig VPS33B (96% identical), rat Vps33b (93% identical), tropical clawed frog vps33b (76% identical), zebrafish vps33b (73% identical), Caenorhabditis elegans vps-33.2 (28% identical), Drosophila melanogaster Vps33B (23% identical). Paralogues in human: VPS33A (33% identical), STXBP2 (18% identical), VPS45 (14% identical), STXBP3 (14% identical), SCFD1 (14% identical), SCFD2 (12% identical).
Diseases named in the same sentence as VPS33B in open-access papers:
VPS33B is named in the same sentence as 38 diseases in open-access papers, as found by Europe PMC text mining. Sharing a sentence is not in itself a finding about the gene and the disease. The quoted sentences say what the papers report.
arthrogryposis (15 papers, 2012 to 2026). A rare, non-progressive congenital disorder characterized by multiple joint contractures which are present at birth. "VPS33B forms a protein complex with VIPAS39 (VIPAR), and mutations in the VPS33B gene cause arthrogryposis-renal dysfunction-cholestasis syndrome." (PMID 39812558, 2025). "This variant was described as compound heterozygous with another nonsense variant in VPS33B within a family affected by arthrogryposis, renal dysfunction, and cholestasis (ARCS1)." (PMID 40870862, 2025). "In some PFIC12 (caused by a variant in the VPS33B gene) patients, arthrogryposis, Renal Dysfunction-Cholestasis (ARC) syndrome, and mildly prolonged aPTT have been observed." (PMID 39984942, 2025). "It has reported that VPS33B has close association with arthrogryposis, renal dysfunction and cholestasis (ARC) syndrome." (PMID 30967781, 2019). "One example is arthrogryposis, renal dysfunction and cholestasis syndrome, which in most patients is caused by VPS33B mutations." (PMID 28082148, 2017). "Indeed, VIPAS39 and VPS33B deficiencies, which cause arthrogryposis, renal dysfunction and cholestasis syndrome (ARC), result in a reduction of LH3-dependent post-translational modification of COLLIV in inner medullary collecting duct cells accompanied by an abnormal ECM deposition." (PMID 30716086, 2019). "Arthrogryposis, Renal dysfunction and Cholestasis (ARC) syndrome is a rare inherited disorder caused by defects in the VPS33B trafficking protein, leading to impaired bile flow, progressive liver disease and early death." (PMID 42321174, 2026). "Arthrogryposis, renal dysfunction, and cholestasis syndrome (ARCS) is a rare autosomal recessive disorder caused by mutations in VPS33B (ARCS1) and VIPAS39 (ARCS2)." (PMID 35151346, 2022). "Patients with mutations in the genes VPS33B and VIPAS39 have been reported with Arthrogryposis, Renal dysfunction and Cholestasis (ARC) syndrome (OMIM #208085 and #613404)." (PMID 29409756, 2018). "VPS33B forms a complex with VIPAR (also known as SPE-39, VIPAS39 or VPS16B), and mutations in either of these proteins can cause arthrogryposis, renal dysfunction, and cholestasis (ARC) syndrome." (PMID 29778605, 2018). "Mutations in VPS33B and VIPAS39 cause the severe multisystem disorder Arthrogryposis, Renal dysfunction and Cholestasis (ARC) syndrome." (PMID 29409756, 2018). "Arthrogryposis, renal dysfunction, and cholestasis syndrome is a multi-system disorder, with some symptoms attributable to the known functions of VPS33B and VIPAR in apical recycling pathways, post-Golgi collagen processing, and α-granule formation in megakaryocytes." (PMID 29778605, 2018).
cholestasis (14 papers, 2012 to 2025). Impairment of the bile flow caused by obstruction within the liver, or outside the liver in the bile duct system. "A mutation in the VPS33B gene leads to ARC syndrome (arthrogryposis–renal dysfunction–cholestasis), which includes renal tubular dysfunction, thrombocytopenia, and cholestasis." (PMID 39273517, 2024). "Mutations in the VPS33B gene can result in abnormal liver cell polarity, leading to bile flow disruption and cholestasis." (PMID 37324459, 2023). "The review focuses specifically on the ABCB11, TJP2 and VPS33B genes due to the important and increasingly well-defined mechanisms by which variants in these genes lead to cholestasis and possibly HCC." (PMID 36010647, 2022). "Biallelic mutations in VPS33B cause arthrogryposis, renal dysfunction and cholestasis (ARC) syndrome." (PMID 36010647, 2022). "Depletion of the Vps33b protein in mouse hepatocytes caused elevated serum bile acids, reproducing the cholestasis presented in ARC." (PMID 33557414, 2021). "Mutations in VPS33B are associated with a neonatal syndrome that includes cholestasis (OMIM 208085)." (PMID 32012846, 2020). "Overall, we concluded that mislocalization of BSEP contributed to cholestasis caused by hepatic Vps33b deficiency." (PMID 30967781, 2019). "We found that hepatic Vps33b depletion caused cholestasis and slight liver injury in mice, which was also commonly observed in ARC patients as previously reported." (PMID 30967781, 2019). "Overall, alterations of bile acids among different tissues characterized the pathogenic conditions of cholestasis in hepatic Vps33b-depleted mice." (PMID 30967781, 2019). "ARC patients with VPS33B mutations show cholestasis with high plasma ALP activity and bile acid levels." (PMID 28082148, 2017). "PFIC12 is caused by a variant in the VPS33B gene, encoding the vacuolar sorting-associated protein 33B; the mutated gene can cause isolated cholestasis with low γGT, neonatal-onset jaundice, and conjugated hyperbilirubinemia, associated with intense pruritus and hepatosplenomegaly." (PMID 39984942, 2025). "Hepatic Vps33b-depleted male mice displayed cholestasis and slight liver damage with increased serum levels of ALT, AST, ALP and T-Bili compared to wild-type mice." (PMID 30967781, 2019). "Using the lipidomic and metabolomic profiles of hepatic Vps33b-null male mice, which displayed cholestasis with elevated serum liver enzymes and total bilirubin and total BAs, demonstrated the importance of VPS33B in BA, glycerolipid, phospholipid, and sphingolipid metabolism." (PMID 32012846, 2020). "Cholestasis is one of the syndrome of ARC, however, the role of hepatic Vps33b deficiency in the bile acids homeostasis and lipid metabolism remains unclear." (PMID 30967781, 2019). "We propose here that VPS33B and VIPAS39 mutation screening in patients with normal GGT cholestasis could facilitate accurate diagnosis and the administration of supportive care at early stage, in addition to provide genetic counseling for the affected families." (PMID 35281816, 2022). "We considered that the VPS33B heterozygous pathogenic variant may have been a contributing factor to disease development in this patient, given a positive family history, the implications of heterozygous variants in PFIC genes, and the clinical presentation of cholestasis." (PMID 40870862, 2025). "Consistent with the widespread organ dysfunction in ARCS, VPS33B has a role in the regulation of intracellular protein trafficking, particularly with abnormal organelle biogenesis on the liver and on the kidney that may ultimately result in cholestasis and tubular disfunction." (PMID 35281816, 2022). "Hepatic Vps33b knockout mice displayed a higher serum ALP level compared to Vps33bflox/flox mice, which is a marker for liver disease, specifically cholestasis." (PMID 30967781, 2019).
cholestasis (continued). "Consequently, we believe that the molecular analysis of the VPS33B and VIPAS39 should be considered in patients with normal gamma-glutamyl transferase cholestasis." (PMID 35281816, 2022). "Thus, we raised awareness of the mild clinical picture of ARCS, and we propose that molecular analysis of the VPS33B and VIPAS39 should be considered in patients with normal GGT cholestasis, and not only for patients with the complete ARCS phenotype." (PMID 35281816, 2022). "Recently, VPS33B variants were identified in patients that presented cholestasis but no other clinical features of classic ARC, underscoring a strong association between VPS33B and cholestasis." (PMID 33557414, 2021). "Without Vps33b expression in the liver, the lipid species were distinct from Vps33bflox/flox mice, which might contribute to the pathology of cholestasis." (PMID 30967781, 2019).
Arthrogryposis - renal dysfunction - cholestasis (9 papers, 2009 to 2026). Arthrogryposis-Renal dysfunction-Cholestasis (ARC) syndrome is a multisystem disorder, characterized by neurogenic arthrogryposis multiplex congenita, renal tubular dysfunction and neonatal cholestasis with low serum gamma-glutamyl transferase activity. "Loss-of-function mutations in VPS33B cause arthrogryposis-renal dysfunction-cholestasis (ARC) syndrome, a rare autosomal recessive disorder with multi-organ involvement, including a characteristic proximal tubular dysfunction in the kidney." (PMID 41686830, 2026). "Arthrogryposis-renal dysfunction-cholestasis (ARC) syndrome is an autosomal recessive disorder caused by VPS33B or VIPAS39 mutations." (PMID 35761207, 2022). "Here, we report the case of a 13-year-old Chinese female with ARC syndrome with novel compound heterozygous mutations of VPS33B." (PMID 35761207, 2022). "The clinical suspicion of ARC Syndrome was confirmed through genetic analysis which showed two de novo mutations in the VPS33B gene: an heterozygous mutation (intron 16–17) c.1225 + 5G > Cp. ?" (PMID 29907094, 2018). "VPS33B mutations are detectable in approximately 75% of patients with a clinical diagnosis of ARC syndrome." (PMID 25239142, 2014). "Arthrogryposis-renal dysfunction-cholestasis (ARC) syndrome is a rare but fatal autosomal recessive multisystem disorder caused by mutations in the VPS33B or VIPAR gene." (PMID 25239142, 2014). "Arthrogryposis-renal dysfunction cholestasis syndrome is a complex disease due to mutation of VPS33B involved in intracellular trafficking and targeting of apical proteins." (PMID 19133130, 2009). "Arthrogryposis-renal dysfunction-cholestasis (ARC) syndrome is an autosomal recessive disorder caused by mutations of the VPS33B encoding the vacuolar protein sorting 33B (VPS33B), which is involved in the intracellular protein sorting and vesicular trafficking." (PMID 33029437, 2020). "This case report contributes to a better understanding of this rare disorder, describes a novel mutation in the VPS33B gene which could be associated to a pronounced renal phenotype in ARC-Syndrome." (PMID 29907094, 2018). "Thus, ARC (arthrogryposis-renal dysfunction-cholestasis) syndrome is caused by mutation in the SNARE protein VPS33B, whose yeast homolog was shown to have a key role in late stages of protein trafficking from the Golgi to the vacuole." (PMID 20305790, 2010). "The joint curvature and renal dysfunction mentioned are characteristic features of another rare disorder called Arthrogryposis-Renal Dysfunction-Cholestasis (ARC) syndrome, which can be caused by mutations in the same VPS33B gene." (PMID 37324459, 2023). "VPS33B or VIPAS39 variants (respectively) were identified in patients with a rare multisystem disorder called arthrogryposis-renal dysfunction-cholestasis (ARC) syndrome." (PMID 33557414, 2021). "Arthrogryposis-Renal dysfunction-Cholestasis syndrome (ARC, MIM#208085) is a rare multisystem disease due to mutations in the VPS33B and VIPAR genes, both involved in maintaining apical-basolateral cell polarity." (PMID 29907094, 2018). "Arthrogryposis-renal dysfunction-cholestasis (ARC) syndrome (MIM 208085), caused by mutations in the VPS33B or VIPAR gene, is a rare autosomal recessive multisystem disorder involving the liver, kidney, skin, and central nervous and musculoskeletal systems." (PMID 25239142, 2014). "It should be noted that not all patients with VPS33B mutations develop ARC syndrome, but those that do may present with these additional symptoms." (PMID 37324459, 2023). "It has been recently demonstrated that a profound defect in phagosome-lysosome fusion caused by Vps16B/Vps33B dysfunction may render patients with ARC syndrome increasingly sensitive to infections by nonpathogenic microbes." (PMID 25239142, 2014).
liver disease (3 papers, 2019 to 2026). "This review will thus explore how three genes that are associated with liver disease in childhood (ABCB11, TJP2 and VPS33B) might play a role in the initiation and progression of HCC." (PMID 36010647, 2022). "Thus, it is clear that VPS33B may play an important role in the liver, and mechanistic studies of VPS33B might be helpful to develop an ARC therapy or address other liver diseases." (PMID 30967781, 2019).
ichthyosis (2 papers, 2016 to 2018). Disorders of cornification that are characterized by visible scaling and/or hyperkeratosis of most or all of the skin. "VPS33B and VIPAR deficiencies lead to range of human phenotypes that always include ichthyosis." (PMID 29409756, 2018). "ARC syndrome caused by VPS33B or VIPAR deficiencies results in abnormal kidney and liver function, extremely dry skin (ichthyosis), defective platelet α-granule biogenesis, osteopaenia and recurrent bone fractures, and death in infancy in the majority of patients." (PMID 27435297, 2016). "The collagen abnormalities identified in skin fibroblasts and tendons consistent with the characteristic ARC features of ichthyosis, arthrogryposis, osteopaenia and bone fractures suggest an important role for VPS33B- and VIPAR-dependent LH3 trafficking in connective tissue." (PMID 27435297, 2016).
acute myeloid leukemia (1 paper, 2022). Acute myeloid leukemia (AML) is a group of neoplasms arising from precursor cells committed to the myeloid cell-line differentiation. "We also confirmed that blocking EV maturation and secretion by acute myeloid leukemia (AML) cells through Vps33b knockout/knockdown suppressed AML cell growth and prolonged disease progression in both a mouse model and patient samples." (PMID 36106632, 2022).
bleeding disorders (1 paper, 2015). "A handful of the candidate defects were present in genes that had previously been associated with platelet bleeding disorders, including P2RY12, VPS33B, GATA1, ANKRD26, HPS1, VWF, and LYST22." (PMID 25556537, 2015).
deafness (1 paper, 2017). An inherited or acquired condition characterized by the complete loss of the ability to hear from one or both ears. "Here, we describe three patients with clinical, molecular, and cellular features of an autosomal recessive PPK, associated with ichthyosis and deafness and caused by mutations in VPS33B, from here on referred to as autosomal recessive keratoderma-ichthyosis-deafness (ARKID) syndrome." (PMID 28017832, 2017). "Therefore, defects in collagen homeostasis in VPS33B deficiency may explain the similarities of both skin and deafness symptoms in patients with ARKID and ARC." (PMID 28017832, 2017).
gastric cancer (1 paper, 2021). A primary or metastatic malignant neoplasm involving the stomach. "circRNA_0005529 (circ_0005529) is derived from vacuolar protein sorting 33 homologue B (VPS33B), and its biological role in gastric cancer (GC) has not been examined." (PMID 33472586, 2021).
gray platelet syndrome (1 paper, 2018). Gray platelet syndrome (GPS) is a rare inherited bleeding disorder characterized by macrothrombocytopenia, myelofibrosis, splenomegaly and typical gray appearance of platelets on Wright stained peripheral blood smear. "VPS33B is involved in the formation of precursor alpha-granules of platelets (both stored and membrane components) and presentation is similar to gray platelet syndrome." (PMID 29907094, 2018).
Hyperkeratosis (1 paper, 2018). Hyperkeratosis is a histopathological term defining a thickened stratum corneum and may be present in many different skin conditions, with many possible overlaps. "Here we demonstrate that both Vps33b and Vipar deficient mice develop a skin disease that is similar to patients with ARC syndrome, with keratinocyte hyperplasia and hypertrophy, hypergranulosis, hyperkeratosis and ultrastructural defects in the SC." (PMID 29409756, 2018).
idiopathic pulmonary fibrosis (1 paper, 2025). Idiopathic pulmonary fibrosis (IPF) is a nonneoplastic pulmonary disease that is characterized by the formation of scar tissue within the lungs in the absence of any known cause. "Fibroblasts derived from idiopathic pulmonary fibrosis (IPF) patients have higher collagen endocytic recycling capacity that is mediated by VPS33B and ITGA11." (PMID 39812558, 2025). "The idiopathic pulmonary fibrosis (IPF) fibrotic focus is positive for integrin α11 subunit and VPS33B." (PMID 39812558, 2025).